CRY1 (cryptochrome circadian regulator 1)
Diseases named in the same sentence as CRY1 in open-access papers (continued):
Sharing a sentence is not in itself a finding about the gene and the disease.
colorectal cancer (9 papers, 2013 to 2022). A primary or metastatic malignant neoplasm that affects the colon or rectum. "High levels of cry1 were associated with the development of metachronous metastasis and worse survival in patients with colorectal cancer." (PMID 36361993, 2022). "Similarly, as in the case of cry1, oncogenic effects were predominantly referred with respect to the cry2 gene, as worse survival was associated with high cry2 expression in colorectal cancer tissue." (PMID 36361993, 2022). "Upregulation of PER2 and CRY1 in gastric cancer and CRY1 in colorectal cancer correlate with more advanced disease states and lymph node metastasis." (PMID 31014368, 2019). "In contrast, the up-regulated expression of CRY1 in colorectal cancer is positively correlated with poor patient outcomes." (PMID 26927666, 2016). "The present study was conducted to investigate the expression of Cry1 and its prognostic significance in colorectal cancer (CRC)." (PMID 23626715, 2013). "Higher expression of Cry1 positively correlated with the aggressive phenotype of colorectal cancer and predicted poor patientoutcomes." (PMID 23626715, 2013). "The link between Cry1 and colorectal cancer cell growth was further established using colony formation assays after Cry1 knockdown." (PMID 23626715, 2013). "Cry1 mRNA expression was at most 10-fold higher in the colorectal cancer cell lines than in the FHC cells." (PMID 23626715, 2013). "Confirmation that Cry1 promoted the migration of colorectal cancer cells was assessed by the transfection of SW480 cells with Cry1-siRNA or negative siRNA." (PMID 23626715, 2013). "As for the Cry1 expression was associated with lymph node status, the effect of Cry1 on the migration of colorectal cancer cells was explored using the transwell assay to examine the effects of Cry1 overexpression or deletion." (PMID 23626715, 2013). "Cry1 protein was highly expressed in the colorectal cancer cell lines and only weakly expressed in the FHC cells." (PMID 23626715, 2013). "We also present experimental evidence that overexpression of Cry1 in colorectal cancer cell lines promoted cell proliferation and migration." (PMID 23626715, 2013). "Under in vivo conditions, cry1 overexpression promoted colorectal cancer growth." (PMID 36361993, 2022). "Based on these findings, we conclude that Cry1 is functionally important in the development and progression of colorectal cancer and that Cry1 may serve as a new target for colorectal cancer therapy." (PMID 23626715, 2013). "In colorectal cancer, the transcriptional levels of CLOCK, CRY1, and NR1D1 were upregulated in 1, 1, and 2 datasets, respectively." (PMID 35116071, 2022). "Our results suggest that overexpression of Cry1 gene could be a useful predictor of lymph node metastasis, TNM stage and poor outcomes in patients with colorectal cancer." (PMID 23626715, 2013). "We, therefore, evaluated the expression levels of Cry1 in human colorectal cancer tissues and matched non-tumor mucosa and analyzed the clinical significance of Cry1 expression inCRC patients." (PMID 23626715, 2013). "Cry1 mRNA was expressed at higher levels in eight of the colorectal cancer tissue samples than in adjacent noncancerous tissues." (PMID 23626715, 2013). "Cry1 mRNA expression in colorectal cancer was investigated using RT-PCR; analyzes of Cry1 mRNA were executed on ten matched pairs of colorectal cancer samples and adjacent noncancerous tissue samples." (PMID 23626715, 2013). "However, studies assessing the relations of Cry1 expression to clinicopathological features and outcomes in colorectal cancer have not been reported." (PMID 23626715, 2013).
glioma (9 papers, 2019 to 2025). A benign or malignant brain and spinal cord tumor that arises from glial cells (astrocytes, oligodendrocytes, ependymal cells). "The researchers studied the impact of CCGs in the development of lower grade glioma and observed that certain genes including RORβ, NPAS2, and CRY1 were linked with elevated or reduced risk of lower grade glioma." (PMID 40495887, 2025). "Importantly, high expression of cluster I and CRY1 was associated with poor survival of glioma patients in both the TGCA and CGGA databases." (PMID 35832846, 2022). "The contributions of the Cry1 gene in glioma biology have been demonstrated in experimental models of Cry1/2 double knockout mouse models under chronic jetlag conditions." (PMID 40495887, 2025). "On the contrary, PER1/2 show lower expression in higher gliomas, and CRY1/2 show lower expression in gliomas compared to normal tissue." (PMID 37400829, 2023). "However, the authors show that glioma cells that are positive for Cry1/2 show an increase in the amount of Cry1/2 with respect to non-tumoral tissue." (PMID 35216153, 2022). "Also, the role of Cry1 on glioma biology has been evidenced in experimental models of Cry1/2 double knockout mice subjected to CJL conditions." (PMID 34361055, 2021). "As the expression level of glioma-related genes was found differentially expressed in the comparison between WT, Bmal1-/- and Cry1/2-KO knockout mice, we suggest that clock genes may have a direct or indirect association with expression patterns of these genes." (PMID 31523185, 2019). "The differential expression of CCGs in glioma grading confirmed that cluster I genes (ARNRL, NPAS2, and TIMELESS) and CRY1, with cluster II genes (CRY2, DBP, NR1D1, NR1D2, PER2, PER3, and RORA) showed significantly opposite expression trends in brain tissues." (PMID 35832846, 2022). "In a study, a downregulated Cry1 expression in gliomas was observed in 69 patient samples as compared to non-tumor cells." (PMID 40495887, 2025). "Using the U251 glioma cell model, we also observed rhythmic transcriptions of the clock genes, including BMAL1, CLOCK, CRY1, and PER1, which adds novel evidence that the biological clock also functions in vitro, suggesting that this cell line is suitable for biological rhythm research." (PMID 38385622, 2024). "A study of 69 sample patients evidenced a downregulated expression of Cry1 in glioma tissues compared with non-tumor cells." (PMID 34361055, 2021).
Insulin resistance (9 papers, 2015 to 2024). Increased resistance towards insulin, that is, diminished effectiveness of insulin in reducing blood glucose levels. "Significant interactions between the CRY1 variant and dietary carbohydrates for insulin resistance in both populations (p < 0.05)." (PMID 36768893, 2023). "Variation in CRY (CRY1 and 2) genes was also associated with susceptibility to T2D, while CRY1 polymorphism increased the risk of systemic insulin resistance in the presence of high carbohydrate intake." (PMID 29385702, 2018). "Cry1 plays a key role in regulating circadian rhythmicity and metabolism, such that Cry-deficient mice become more obese and develop insulin resistance in response to a high fat diet relative to wild-type controls." (PMID 25830335, 2015). "Similarly, thiazolidinedione resolves the disruption of the expression of circadian clock-associated genes(Bmal1, Per2, Cry1), improving insulin resistance." (PMID 39165284, 2024). "Besides, previous studies show the CRY1 variant is associated with CVDs risk factors such as hypertension, hypertriglyceridemia, hypercholesterolemia, hyperglycemia, and insulin resistance." (PMID 37580741, 2023). "CRY1 rs2287161 represents an example of gene–diet interaction for insulin resistance in Mediterranean and North American populations." (PMID 36768893, 2023). "The CC carriers of CRY1 rs2287161 that ate high amounts of carbohydrates showed higher insulin resistance when compared to G carriers whose values of model assessment of insulin resistance (HOMA-IR) were independent of carbohydrate intake, remaining constant." (PMID 36768893, 2023).
Arthritis (8 papers, 2012 to 2025). Inflammation of a joint. "Global deletion of Nfil3, Cry1 and/or Cry2 worsens disease severity in experimental arthritis models." (PMID 38981514, 2024). "Consistently, expression of CRY1 was markedly decreased by administration of melatonin, subsequently aggravated in mouse antitype ΙΙ collagen antibody-induced arthritis." (PMID 24901009, 2014). "CRY1 is a circadian clock-related gene that also plays a part in arthritis." (PMID 35886000, 2022). "Once treated with anti-TNF-α antibodies, Cry1−/−Cry2−/− mice progression of arthritis was halted, suggesting that the circadian rhythm and arthritis affect each other, and disruptions in the circadian rhythm mouse clock genes Cry1 and Cry2 may hasten the progression of inflammatory arthritis." (PMID 37378201, 2023). "To verify the significance of increased wee-1 expression in CRY knockout mice (CRY1−/− CRY2−/− mice), we utilized a mouse model of arthritis." (PMID 24901009, 2014). "Since circadian clock genes were reported to be closely related to the pathogenesis of arthritis and excessive expression of Per2 could induce apoptosis, we examined the effect of MTX on expression of Per2, Bmal1, Clock, and Cry1 that were regarded as “core” clock genes." (PMID 29566767, 2018). "Mice lacking CRY1 and CRY2 have increased levels of activated T cells, and when arthritis was induced in these mice, serum IL6 levels were higher than in wild type mice with induced arthritis." (PMID 35886000, 2022).
osteosarcoma (8 papers, 2014 to 2024). A usually aggressive malignant bone-forming mesenchymal neoplasm, predominantly affecting adolescents and young adults. "However, downregulation of cry1 caused an increase in osteosarcoma cell proliferation and migration and stimulated tumour growth in nude mice under in vivo conditions." (PMID 36361993, 2022). "Herein, the same core circadian clock genes that are rhythmically controlled by CRY1 in osteosarcoma cells are also bound by CRY1 in PCa (i.e., CRY1, CRY2, PER2, and PER3) showing concordance of binding across models regardless of circadian synchronization." (PMID 33452241, 2021). "Genome-wide understanding of CRY1 function is poorly understood, and in humans has been limited to a single osteosarcoma model." (PMID 33452241, 2021). "The importance of CRY1 on DNA repair in osteosarcomas has yet to be studied." (PMID 33452241, 2021). "In this connection, in the human osteosarcoma U2OS cell line, BMAL1 KD diminished metabolite rhythms, while CRY1 or CRY2 perturbation generally shortened/lengthened rhythms, respectively." (PMID 36183836, 2022). "CRY1 ubiquitination by DDB1-CUL4A was also observed in mouse hepatoma Hepa1 cells and human osteosarcoma U2OS cells, indicating that such regulation is conserved in multiple cell types." (PMID 26431207, 2015). "We selected the immortalized human osteosarcoma cell line U2OS to identify and characterize binding sites of the circadian transcription factor CLOCK/BMAL1 and its inhibitor CRY1 by chromatin immunoprecipitation and next generation sequencing (ChIP-seq)." (PMID 25007071, 2014).
gastric cancer (7 papers, 2015 to 2022). A primary or metastatic malignant neoplasm involving the stomach. "In addition, up-regulation of CRY1 expression was markedly associated with the advancement of clinical stages of gastric cancer." (PMID 26253128, 2015). "Among Han Chinese gastric cancer patients, SNP rs1056560 in the CRY1, under an additive model had a protective effect on the overall survival of the patients with a HR of 0.72 (95% CI 0.58–0.88, p = 0.021)." (PMID 31739444, 2019). "Researchers reported that PER2 and CRY1 were significantly upregulated in gastric cancer." (PMID 34721627, 2021). "Despite some contradictory reports in CRC models, oncogenic features are usually attributed to cry1 in respect to CRC and gastric cancer progression." (PMID 36361993, 2022). "In contrast, PER2 is upregulated in gastric cancer (GC), as is CRY1 in the advanced stages of GC." (PMID 33114496, 2020). "The up-regulation of BMAL1, CLOCK, and PER in gastric cancer and the up-regulation of CRY1 in more advanced stage gastric cancer but not in the earlier stage has also been reported." (PMID 34966277, 2021).
metabolic syndrome (7 papers, 2015 to 2024). A cluster of metabolic risk factors for CARDIOVASCULAR DISEASES and TYPE 2 DIABETES MELLITUS. "Metabolic syndrome in humans is associated with the transcription of CRY1 and PER2 in adipose tissue." (PMID 32050674, 2020). "Murine cry1 and cry2 gene deletions are associated with disruptions in the circadian rhythmicity of insulin and glucagon secretion, which in turn are associated with insulin resistance, hypertension and impaired glucose tolerance and dyslipidemia." (PMID 36034454, 2022). "Other studies have shown associations between CRY1 and CRY2 polymorphisms and blood pressure in patients with metabolic syndrome, or associations between PER2 and BMAL1 polymorphisms and the non-dipper phenotype in 372 young hypertensive patients." (PMID 37298261, 2023). "Clock genes are linked directly to metabolic syndromes; polymorphisms circadian clock genes CLOCK, BMAL1, Per1/2 and Cry1/2 have been associated with metabolic disorders, including neuropsychiatric or neurodegenerative diseases." (PMID 33184471, 2020). "Changes in Per2, Bmal1 and Cry1 mRNA expression are related to human metabolic syndrome." (PMID 25799429, 2015).
ovarian carcinoma (7 papers, 2012 to 2024). A malignant neoplasm originating from the surface ovarian epithelium. "Evidence suggests that, controlling for stage, histological subtype, and grade, low BMAL1 and CRY1 expression together significantly predict lower overall survival in ovarian cancer patients." (PMID 26807442, 2015). "A report shows that the combination of low CRY1 and low BMAL1 expression were prognostic factors in ovarian cancers, however, neither CRY1 nor BMAL1 were linked with the survival rates of patients suffering from ovarian cancers." (PMID 31151182, 2019). "As CRY1 had been previously shown to undergo aberrant DNA methylation events in various solid human malignancies including breast and ovarian cancers, we examined whether epigenetic silencing could also explain the observed CRY1 mRNA expression differences in CLL subgroups." (PMID 22470559, 2012). "Expression levels of the CRY1 and BMAL1 core-clock genes were correlated with clinical parameters in epithelial ovarian cancer." (PMID 36385012, 2022). "We further evaluated the correlations between PER1 and these 10 interacting proteins based on the GEPIA database and found that the expression of PER1 in ovarian cancer was correlated with that of ARNTL, CLOCK, CRY1, CRY2, CSNK1D, CSNK1E, NPAS2, and PER3." (PMID 34220965, 2021).
atherosclerosis (6 papers, 2016 to 2024). A disease characterized by the build-up of fatty material and calcium deposition in the arterial wall resulting in partial or complete occlusion of the arterial lumen. "Besides Bmal1 and Clock, also the clock genes Nr1d1, Cry1/2, and Rora, have been implicated in atherosclerosis." (PMID 38484032, 2024). "CRY1 mRNA expression is significantly lower in patients with atherosclerosis, while augmented CRY1 expression reverses the atherosclerotic process by the Toll-like receptor (TLR)/nuclear factor kappa-B (NF-κB) pathway." (PMID 35111358, 2022). "It is noteworthy that patients exhibiting atherosclerotic plaques display lower blood cell Cry1 mRNA levels compared to the controls, acknowledging the protective effect of Cry1 against atherosclerosis in humans as well." (PMID 34575881, 2021). "Furthermore, the global adenovirus-mediated overexpression of Cry1 in ApoE−/− mice protects against the development of atherosclerosis through a TLR/NF-κB-dependent mechanism." (PMID 34575881, 2021). "While it’s been reported that the demethylase FTO (alpha-ketoglutarate-dependent dioxygenase) coimmunoprecipitates with CRY1/2, studies also showed that upregulation of FTO and CRY1 attenuated atherosclerosis through macrophages and proinflammatory factors respectively." (PMID 34082770, 2021). "In this study, we revealed that RORB, RORC, PER1, CRY1, FTO were in close relationship with atherosclerosis, particularly in atherosclerotic lesions with higher immune infiltration." (PMID 34082770, 2021). "All the available evidence suggests that chronopharmacology-based therapy targeting RORB, RORC, PER1, CRY1, or FTO might constitute another approach for the treatment of atherosclerosis." (PMID 34082770, 2021).
bipolar disorder (6 papers, 2010 to 2025). A disorder of the brain that causes unusual shifts in mood, energy, activity levels and the ability to carry out day-to-day tasks. "Several core clock genes, such as PER1, PER3, CRY1, and CRY2, have been found to be associated with bipolar disorder." (PMID 39454958, 2024). "Phase control through the melatonin-guided interval of Per1/Per2 to Cry1/Cry2 expression peaks may have relevance to mood disorders, as the internal alignment and the melatonin signal (amplitude and phase) are abnormal in patients with bipolar disorder and those with winter depression in particular." (PMID 20195522, 2010).
hepatocellular carcinoma (6 papers, 2016 to 2022). A malignant tumor that arises from hepatocytes. "In mouse hepatoma cells, the knockdown of Ddb1 or overexpression of the ubiquitination-defective mutant CRY1 K585A enhances CRY1 stability and increases the amplitude of circadian oscillations as measured by a Bmal1-Luc reporter." (PMID 36142478, 2022). "The impact of clock associated lncRNAs in hepatocellular carcinoma showed that the lncRNA HULC upregulates the expression levels of CLOCK and its downstream targets, like PER1 and CRY1 in hepatoma cells in vivo." (PMID 32344623, 2020). "To examine whether CRY1, a novel target gene of SREBP1c, might modulate hepatic gluconeogenic gene expression, we suppressed CRY1 expression via small interfering RNA (siRNA) in rat hepatoma H4IIE cells." (PMID 27412556, 2016). "For example, Cry1 and Cry2 overexpression was associated with poor OS in gastric cancer and CRC; Npas2 was frequently upregulated in hepatocellular carcinoma (HCC) and its overexpression significantly contributed to poor prognosis of HCC patients." (PMID 32437452, 2020).
Hypertension (6 papers, 2017 to 2021). The presence of chronic increased pressure in the systemic arterial system. "In Hispanic/Latinos, the rs6850524 in Clock was associated with increased risk for hypertension, meanwhile rs12649507, rs4864546, and rs4864548 reduced the risk, also rs8192440 (Cry1) reduced the risk for type 2 diabetes." (PMID 34141862, 2021). "Furthermore, Kovanen found an association of Cry1 with arterial hypertension and elevated blood pressure." (PMID 30235329, 2018). "Emerging evidence suggested that clock genes such as Baml, Ck1e, Cry1, Per1 and Per2 play an integral role in the development of hypertension and kidney disease." (PMID 28368364, 2017). "In contrast, gene expression profiling of Spontaneously Hypertensive (SHR) rats, a genetic model of hypertension, demonstrated decreased expression of Bmal1 and Npas2, while Per1, Per2, Per3, Cry1, Cry2, Bhlhe41 and Csnk1D were all upregulated compared to naïve WKY controls." (PMID 33127986, 2020). "More studies should be done in order to look into the role of circadian rhythm especially Cry1 and Ngb in OSA and hypertension." (PMID 30235329, 2018). "Ngb and Cry1 are down regulated in OSA with PA, although the mechanism of hypertension and PA is still unknown." (PMID 30235329, 2018).